LEPR (leptin receptor)
Diseases named in the same sentence as LEPR in open-access papers (continued):
Sharing a sentence is not in itself a finding about the gene and the disease.
Obesity (continued). "We used two mouse models of obesity-related inflammation (i.e., leptin receptor deficient db/db mice and mice with diet-induced obesity, DIO)." (PMID 23166823, 2012). "Mutations in the leptin receptor gene cause severe obesity and insulin resistance in rodents and humans." (PMID 22969821, 2012). "Inactivating mutations of leptin or leptin receptor gene result in the body's false perception of starvation and subsequent hyperphagia, decreased energy expenditure, and severe obesity." (PMID 22518191, 2012). "Accordingly, we investigated to which extent high leptin levels and low grade inflammation- associated ER stress – two markers linked to obesity – take effect on leptin receptor availability for sOb-R generation." (PMID 22545089, 2012). "These db/db mice are leptin receptor deficient and represent a model of type II diabetes mellitus characterized by hyperglycemia, obesity, hyperinsulinemia, and impaired wound healing." (PMID 22879874, 2012). "LEPROT is involved in the cell-surface expression of the leptin receptor, regulation of growth hormones linked to obesity in mice, and cell signaling in response to circulating nutrient levels." (PMID 22577559, 2012). "To investigate the potential consequences of decreased SIRT1, we utilized db/db mice, a genetic model of obesity and insulin resistance resulting from a leptin receptor mutation." (PMID 23137106, 2012). "We therefore performed a systematic review and meta-analysis on the association between the three LEPR variants Q223R, K109R and K656N and obesity-related outcomes." (PMID 22028824, 2011). "For this purpose we have used a well established genetic model of obesity and insulin resistance, the obese Zucker rat, characterized by a missense mutation in the leptin receptor and associated with several cardiovascular complications." (PMID 21513515, 2011). "We searched electronic databases, including population-based studies that investigated the association between LEPR variants Q223R, K109R and K656N and obesity- related phenotypes in healthy, unrelated subjects." (PMID 22028824, 2011). "Leptin deficiency in humans either due to an absolute shortage of leptin or due to leptin-receptor mutations causes severe early onset obesity, hyperphagia, hyperinsulinemia, hypogonadism, and impaired T cell function." (PMID 20871818, 2010). "In rodents, leptin receptor gene mutations resulted in obesity, hyperglycemia, hyperinsulinemia, and reduced fertility." (PMID 20624279, 2010). "This study reports the relationship of leptin receptor polymorphisms on obesity and type 2 diabetes for the first time in the local population." (PMID 21031055, 2010). "On the other hand, beneficial phenotypes for obesity-related traits and total cholesterol levels were associated with higher DNA copy numbers (2X) of the LEPR gene locus in male subjects." (PMID 20624279, 2010). "One such attractive and popular Single Nucleotide Polymorphism (SNP) candidate for obesity is the gene coding for leptin receptor." (PMID 21031055, 2010). "As such, leptin levels are directly proportional to BMI and patients deficient in either leptin or leptin receptor are characterized by marked obesity." (PMID 20585554, 2010). "Common genetic variants (e.g., SNPs) at the LEPR gene locus have been associated with obesity, hyperinsulinemia, type 2 diabetes mellitus (T2DM), and variations in leptin levels in different populations." (PMID 20624279, 2010). "Sequencing-based detection of LEPR mutations demonstrated that frame-shift or missense mutations of the LEPR gene caused obesity, pituitary dysfunction, hyperphagia, or hypogonadism in humans." (PMID 20624279, 2010). "The leptin receptor gene (LEPR) polymorphism plays an important role in obesity and type 2 diabetes." (PMID 21031055, 2010). "Dissociation of apoD with the leptin receptor is linked to thedevelopment of obesity in leptin receptor-deficient db/db mice." (PMID 19946382, 2009).
Obesity (continued). "For example, in a study of 3,653 residents of Osaka, Japan, researchers showed the LEPR Arg109Lys SNP was associated with obesity such that individuals with the 109Lys/Lys genotype were at increased risk compared to those with the 109Arg/Arg genotype." (PMID 19818126, 2009). "For example among Taiwanese aboriginal populations, greater incidences of obesity were associated with the G-2548A polymorphism in the promoter region of the leptin gene and the Gln223Arg (Q223R) polymorphism of the leptin receptor gene." (PMID 16942616, 2006). "For example, the Leprdb and Lepob-TGFα transgenic mouse model, used to investigate the effects of obesity on tumorigenesis, are leptin deficient or have a leptin receptor defect." (PMID 16168107, 2005). "Obesity in the Zucker rat is inherited as an autosomal-recessive trait caused by a mutation (fa) in the leptin receptor gene, discovered by Zucker and Zucker." (PMID 16168107, 2005). "The failure of hyperleptinemia to decrease adiposity in common forms of obesity has led to the notion that impaired leptin receptor (LepRb) signaling ("leptin resistance") might cause obesity." (PMID 42082152, 2026). "Also, multiple mutations in the leptin receptor have been identified in patients presenting with early-onset severe obesity and hyperphagic behavior." (PMID 41441006, 2025). "Chronic activation of ArcGABA non-LepR neurons led to massive obesity, which was associated with normal leptin-induced pSTAT3 signaling but phenotypic leptin resistance; i.e., high leptin levels failing to reduce obesity." (PMID 40540394, 2025). "ER stress downregulates leptin expression and inhibits leptin receptor signaling, contributing to leptin resistance, increased appetite, and reduced energy expenditure.This resistance is associated with obesity-induced ER stress and the dysfunction of the mitochondria-ER interaction." (PMID 41567335, 2025). "In contrast, rare case reports highlight monogenic obesity linked to leptin, LEPR, and POMC genes." (PMID 40077044, 2025). "Thus, mutations in the leptin receptor gene, which mediate an increased risk of severe obesity, are likely associated with the development of eosinophilic and neutrophilic endotypes of asthma, with the latter being more prevalent." (PMID 40361972, 2025). "The db/db mouse, one of the earliest and most extensively studied models of diabetes, carries a mutation in the leptin receptor, resulting in hyperphagia, pronounced obesity, and insulin resistance beginning at three weeks of age, with persistently elevated blood glucose levels." (PMID 40647186, 2025). "Thus, early genetic studies of severe obesity (SevO) focused on identifying gene-disrupting mutations in the leptin-melanocortin pathway (e.g., LEPR, MC4R, POMC), which are linked to early-onset SevO through dysregulation of food intake and food preferences." (PMID 40939575, 2025). "Genetic factors such as FTO, MC4R, and LEPR polymorphisms may further influence susceptibility to obesity." (PMID 41228239, 2025). "Obesity has been associated to mutations in the leptin and leptin receptor genes." (PMID 40002424, 2025). "Personalized treatment strategies could be developed to modulate adiponectin and leptin receptor pathways, particularly in obesity‐associated endometrial cancer." (PMID 40642843, 2025). "A recent study identified that the allelic frequencies of the fat mass and obesity-associated (FTO) polymorphism FTO rs9939609 (A) and the leptin receptor polymorphism LEPR rs1137101 (223R) are correlated with an elevated risk of obesity among the Egyptian population." (PMID 41423640, 2025). "Furthermore, the identification of obesity-risk rare variants, including mutations in the leptin receptor gene (LEPR) as well as POMC and MC4R genes, has highlighted that the leptin–melanocortin pathway is a key appetitive control circuit." (PMID 41190296, 2025). "Mutations in leptin or its receptor (LepR) are known to cause infertility and obesity in mice." (PMID 40130278, 2025).
Obesity (continued). "LEPR Gln223Arg polymorphism may influence obesity in female survivors of childhood ALL, particularly those exposed to CRT." (PMID 41228239, 2025). "Furthermore, currently we are moving toward genetic models of obesity, such as ob/ob mice (leptin-deficient) and db/db mice (leptin receptor–deficient), both of which have a C57BL/6 genetic background." (PMID 40565216, 2025). "Mutations in LEP or LEPR lead to severe, early-onset obesity." (PMID 41150735, 2025). "Polymorphism or mutation in LEPR gene are associated with changes in diet and obesity." (PMID 41256167, 2025). "Zucker rats with obesity are deficient for the gene coding for the leptin receptor." (PMID 39375529, 2025). "Mouse studies have demonstrated that obesity is associated with hypothalamic resistance to leptin signaling due to leptin receptor down-regulation, and have found that the infertility associated with obesity can be rescued by exogenous gonadotropin administration." (PMID 40755647, 2025). "LEPR SNPs c.2002C>T (genotyped by pyrosequencing), located in exon 14, showed strong associations with backfat in Iberian × Meishan and Landrace pig populations, and demonstrated that the T allele in c.2002C>T is a marker for a tendency toward obesity." (PMID 40805060, 2025). "To assess whether Ythdc1 expression in iBAT is associated with obesity, we examined YTHDC1 protein levels in two mouse models of obesity: high-fat diet (HFD)-induced obesity and leptin receptor-deficient db/db mice." (PMID 40355558, 2025). "Thus, our results support a model in which Arc LepR and non-LepR neurons represent two parallel pathways in mediating body weight, and activation of either is sufficient to cause obesity." (PMID 40540394, 2025). "In addition, research has shown that severe leptin resistance is a major factor in the development of chronic hyperglycemia, which can lead to obesity and insulin resistance in leptin receptor-deficient Zucker rats, in addition to hyperglycemia." (PMID 40906133, 2025). "Indeed, the comprehensive clinical evaluations of children deficient for LEP or LEPR from consanguineous families of Pakistan have unveiled a broader health impact of these mutations beyond obesity." (PMID 39237720, 2025). "ZDF rats are a well-established monogenic obesity model of T2D, which is derived from the Zucker fatty (ZF) rat carrying a mutation in the leptin receptor gene (Lepr) and represents metabolic syndrome with sustained and early-onset hyperglycemia and progression to β-cell death." (PMID 39457110, 2024). "As the leptin receptor is expressed on vagal sensory neurons, obesity associated hyperleptinemia could therefore impact on the mechanism described here or change CGRPβ expression." (PMID 38880827, 2024). "Therefore, the results obtained in this study cannot be directly translated to patients, although there are some rare congenital LEPR or leptin mutations in humans that can lead to overeating, obesity, and T2DM." (PMID 39317805, 2024). "However, contrary to this finding, there are also studies showing that common polymorphisms in the LEP gene and the leptin receptor (LEPR) gene play an important role in obesity and obesity-related metabolic biomarkers." (PMID 39594868, 2024). "In addition, we further demonstrated the separation of diabetes and obesity after metabolic surgery through leptin receptor deficiency." (PMID 38302999, 2024). "The sex-specific effects of variants at the LEPR on the development of obesity have been reported." (PMID 39160621, 2024). "Both variants reduce the function of LEPR, leading to a higher risk of obesity development." (PMID 38474283, 2024). "Finally, in contrast to anorexigenic POMC neurons, a BNC2-specific knockout of LepR causes significant hyperphagia and obesity." (PMID 39478220, 2024). "The obesity, hyperinsulinemia and hyperglycemia presented in the Koletsky rats arise from the genotype of the homozygous recessive trait designated as fak resulting from a mutation in the leptin receptor." (PMID 39273348, 2024).
Obesity (continued). "Indeed, a direct role for NG2-glia in the ME for neuronal function has already been indicated, whereby their ablation is associated with obesity attributed to degeneration of the dendritic processes of arcuate nucleus leptin receptor neurons." (PMID 39325695, 2024). "Zucker rat is a model of obesity induced by a spontaneous mutation of the leptin receptor." (PMID 38939902, 2024). "Interestingly, seven of eight heterozygotes carrying the 80 kb deletion were overweight, which is consistent with previous observations that heterozygous human carriers of leptin or leptin receptor mutations are predisposed to overweight and obesity." (PMID 39771044, 2024). "Several studies demonstrated that leptin or its receptor deficiency causes rare, autosomal recessive forms of severe, early-onset obesity, furthermore, obese patients with leptin receptor mutation have poor weight loss or significant weight regain after metabolic surgery." (PMID 38302999, 2024). "Importantly, LepR+ BMSCs were shown to be more abundant in humans with obesity subjects associated with an enrichment of the molecular signature of adipocyte progenitor cells." (PMID 38704393, 2024). "To date, different mutations of the human leptin receptor have been reported and, in most cases, subjects present severe obesity, alterations in immune function, and delayed puberty due to hypogonadotropic hypogonadism with serum leptin levels in the range predicted by their raised fat mass." (PMID 36674935, 2023). "Similarly, Zucker (fa/fa) rats have a spontaneous mutation in the leptin receptor that leads to hyperphagia, severe obesity, and insulin resistance." (PMID 37373143, 2023). "However, little is understood about how leptin acts on the leptin receptor (obR) in neutrophilic airway inflammation in obesity-associated asthma." (PMID 37488474, 2023). "It is suggested that leptin receptor degradation is another mechanism of leptin resistance in obesity and aging, and it could be associated with increased activity of the matrix metalloproteinase-2 (Mmp-2)." (PMID 38068822, 2023). "Previous research supports the idea that the LEPR rs1137101 G > A polymorphism is linked to obesity and may predict variations in body composition." (PMID 38198642, 2023). "Indeed, some authors report that the obesity caused by the leptin receptor gene (Lepr) knockout increases depressive-like immobility in Leprdb/Leprdb mice." (PMID 37371543, 2023). "Likewise, PKCδ inhibited insulin signaling and increased glucose uptake in a mice model of obesity due to leptin receptor mutation." (PMID 37611829, 2023). "These leptin and leptin receptor-deficient rodent models have provided many useful insights into the underlying molecular and pathophysiological mechanisms of metabolic and cardiovascular diseases associated with obesity and type 2 diabetes." (PMID 36978976, 2023). "The Zucker Diabetic Fatty (ZDF) rat is a common model created through mutation in the leptin receptor gene, leading to hyperphagia and obesity, accompanied by hyperinsulinemia, hyperglycemia, peripheral insulin resistance, abnormal lipid metabolism, moderate hypertension, and proteinuria." (PMID 37723622, 2023). "Moreover, a population-based case control study among 574 psoriasis subjects of Hungarian origin demonstrated the link between the LEPR gene polymorphism (rs1137101) and obesity prevalence among patients with early disease onset." (PMID 36980866, 2023). "This neural defect leads to less repression of food intake and uncontrolled leptin-regulated fat storage; thus, the dysregulation of leptin receptor activity upon loss of Magel2 may be the underlying cellular mechanism for obesity in PWS." (PMID 37685915, 2023). "LAT1 in LepR-expressing neurons is implicated in HFD-induced obesity and metabolic dysfunction." (PMID 36862514, 2023).
Obesity (continued). "Overall, the study concluded that heterozygous variants involving PCSK1, POMC, LEP, and LEPR are common among adult patients with class III obesity and occasionally may exhibit a phenotype similar to that of homozygotes." (PMID 37835041, 2023). "We therefore investigated the expression of the seven hepatokines uncovered by our proteomic analysis in the liver of a genetic mouse models of obesity, steatosis and IR/T2D, i.e., ob/ob mice (mice deficient for leptin) and db/db mice (mice deficient for leptin receptor)." (PMID 35409319, 2022). "Both the LEP G2548A and LEPR Q223R variants were related to the increase in obesity risk." (PMID 36551995, 2022). "LEPR perturbations cause obesity, and LepR+ endothelial niches support HSC survival." (PMID 35166671, 2022). "Indeed, hepatocyte hypertrophy/steatosis and hepatomegaly are also observed in genetic (e.g., leptin (ob/ob) or leptin receptor (db/db) deficient mice) and diet-induced mouse models of obesity and IR." (PMID 35409319, 2022). "First, mutations in the leptin receptor are a rare cause of obesity and T2DM in humans." (PMID 36572735, 2022). "Additionally, several LEP and LEPR polymorphic profiles are associated with obesity, with only a small number of patients with early-onset extreme obesity being reported." (PMID 35563103, 2022). "Compared to lean controls, mRNA levels of GPSM1 in both epididymal WAT (eWAT) and subcutaneous WAT (scWAT) were significantly higher in mice with high-fat diet (HFD)-induced obesity (DIO) or genetic obesity caused by leptin (Ob/Ob) or leptin receptor (Db/Db) deficiency." (PMID 36434066, 2022). "However, obesity conditions with leptin deficiency or leptin receptor deficiency suppressed endometriosis development." (PMID 36140261, 2022). "Therefore, leptin receptor (LepR) signaling in DMH neurons is likely involved in the pathophysiology of hypertension that is associated with obesity." (PMID 35742928, 2022). "In addition, mice leptin-deficient ob/ob or leptin receptor (LepRb)-null db/db mice present hyperphagia, obesity, and alterations in the gut microbiota." (PMID 36153588, 2022). "Specifically, Mt remodeling in hypertensive and insulin-resistant lean models (Ren2 rat models), lean mice with streptozotocin-induced diabetes, obesity models including diet-induced obesity, genetic leptin-deficient ob/ob, and leptin receptor-deficient db/db diabetic mice are examined." (PMID 35563211, 2022). "A loss of hypothalamic LepR activity is the driving cause of hyperphagic obesity in the db/db mouse model and believed to contribute to both decreased satiety and increased leptin secretion in the state of obesity." (PMID 36111295, 2022). "The age group of 6–10 years can also provide us with an opportunity for early detection of obesity, especially in highly susceptible populations with a potential of methylation of LEPR as a biomarker, as the analysis of the ROC curve showed LEPR methylation has very good diagnostic accuracy." (PMID 36360268, 2022). "This study investigated the preventive effect and mechanism of long-term intervention of Huangshan Maofeng green tea water extract (HTE) on obesity-associated metabolic disorders in leptin receptor knockout (Lepr−/−) rats by using gut microbiota and hepatic lipidomics data." (PMID 36230016, 2022). "The leptin receptor is a transmembrane protein that can transduce the brain leptin signaling system, and previous studies have linked lower leptin receptor concentrations to obesity." (PMID 34419464, 2022). "However, the PMR of the gene LEPR was significantly associated with all the obesity measures after adjusting the maternal education and family income only in AA children." (PMID 36360268, 2022). "Both LEP 2548AA and LEPR Q223R were positively correlated with obesity risk." (PMID 36551995, 2022).